TNF (tumor necrosis factor)
Diseases named in the same sentence as TNF in open-access papers (continued):
Sharing a sentence is not in itself a finding about the gene and the disease.
tumor (continued). "Next, we aimed to investigate whether a conventional CD3 bispecific T cell engager format added to PBMCs without OVCAR-3 tumor cells being present would induce the release of IFN-γ and TNF-α." (PMID 40755782, 2025). "However, splenic uPA–/– CD8+ T cells selectively upregulated IFN-γ production but showed no concurrent increase in GzmB or TNF-α levels, suggesting that CD8+ T cells cytotoxicity in this context was tumor microenvironment-dependent." (PMID 40959092, 2025). "Upon inhibition of TNF signaling, VPM1002 failed to induce tumor clearance and apoptosis." (PMID 39114912, 2024). "Despite the importance of NF-κB in tumor promotion, no primary-level studies have been published to date on its relevance in OLP, although some of the cytokines and enzymes tributary to its actions (TNF-α and COX-2) have been studied." (PMID 39123342, 2024). "In particular, our investigation into its role in immune escape mechanisms uncovered a significant positive correlation with immune-suppressive cytokines (TGF-β, IL-10, and IL-1β) and a negative correlation with anti-tumor cytokines (IFN-γ, IL-2, and TNF-α) in metastatic lung cancer." (PMID 38951802, 2024). "DC matured by co-culture with 1B3-transfected HCT116 induced production of the type 1 cytokines IFNγ and TNFα, and proliferation (expressed as percentage CTVlow cells) by CD4+, CD8+, and CD4-CD8- T cells whereas DC matured by mock or 3A1-transfected tumor cells had no or limited effect." (PMID 39007281, 2024). "Interestingly, the Caki-1 RCC spheroids did not express TNF-α, and the enhanced TNF-α production indicated that RCC cells exacerbate the immune activation initiated by the S protein in the non-tumor cells." (PMID 39768130, 2024). "Interestingly, CQ treatment did not alter the level of IFN-γ+ TNF-α+ CD4+ T cells and PD-1+ T cells infiltrated into the tumor." (PMID 39247196, 2024). "At 24 h and 48 h, untransduced T cells failed to eradicate tumor cells, while the transduced OVA-TCR expressing T-cells showed significant cytotoxicity against B16-OVA cells and secreted elevated levels of effector cytokines such as IFN-γ and TNF-α." (PMID 38173045, 2024). "Tumor necrosis factor-related apoptosis-inducing ligand (TRAIL) is a member of the tumor necrosis factor (TNF) family of death ligands, and it binds to death receptor 4/5 (DR4/5) to selectively initiate caspase-8 (CASP 8)-dependent extrinsic apoptosis in tumor cells without affecting normal cells." (PMID 38909249, 2024). "The immunosuppressive cytokine milieu was rich in IL-10 and TNF-α in HPV-negative but not in HPV-positive HNSCC; the resulting functional impairment of tumor-infiltrating pDCs further supported the immunosuppressive TME by promoting the expansion of Tregs in the tumor tissue." (PMID 39020402, 2024). "However, in the off-tumor condition, the concentrations of IFN-γ, IL-6, and TNF-α released from MB2033-treated hPBMCs were lower (data not shown) than those released following the treatment of aldesleukin or αPD-L1 × non-α IL-2v." (PMID 38834889, 2024). "The absence of tumor cell 11β-HSD1 also resulted in CD8+ T cells with an increased fraction of effector memory cells (Tems) and increased production of the proinflammatory cytokines IFN-γ and TNF-α." (PMID 37471141, 2023). "Differently, differences between the two subsets were clearly less evident at the NT and even not significant in the tumor site, either in terms of IFN-ɣ, TNF-α and polyfunctionality, with a partial functional advantage of PD1+CD28− T cells only in terms of GrzB (P < 0.003)." (PMID 37898752, 2023). "Similarly, stimulation of mBMMs adhered to complex-tumor-derived CDMs with and without TNC and with CCL2 did not induce TNFα production regardless of the TNC content of the matrix." (PMID 37176074, 2023).
tumor (continued). "In contrast to the nontargeted TPA.TNFα, where the tumor vasculature remained intact, the groups of mice treated with either RGD4C.TPA.TNFα or chemovirotherapy showed extensive vascular damage as shown by the massive reduction in the tumor vasculature." (PMID 37331004, 2023). "Indeed, the same study revealed a correlation with a bad prognosis of TNFα-negative, VEGF-producing MCs in the other tumor types analyzed, including lung, colon, pancreas, and kidney." (PMID 37376140, 2023). "Many studies shown that activated T lymphocytes secrete IFN-γ, which can directly inhibit the proliferation of tumor cells and boost the expression of TNF-α; TNF-α can selectively destroy tumor cells or permit not-yet-diseased cells to move into an anti-tumor condition in a paracrine manner." (PMID 36761888, 2023). "Thus, to confirm the role of TNFα signaling in tumor resistance to CTL killing in our model, we assessed tumor cell survival in presence or absence of a TAK1 inhibitor (Takinib)." (PMID 37732732, 2023). "TLR4, IL-6 and TNF-α expression was upregulated by palmitic acid in a neuroblastoma cell line in vitro and in vivo, TLR4-/- colorectal cancer (CRC) tumor growth was not affected by a diet enriched with palmitic acid, while wild-type CRC tumor growth was increased upon dietary intervention in mice." (PMID 36830818, 2023). "Similarly, we did not observe any difference in IFNγ or TNFα production between TIGIT+ and TIGIT− NK cells in response to cytokine stimulation, suggesting that these TIGIT+ NK cells have greater anti-tumor but not general responsiveness." (PMID 37345049, 2023). "In addition, we found that tumor cells lacking TNFR2 are not more sensitive to cytokine-mediated death, such as that mediated by IFN-γ and TNF-α." (PMID 35260434, 2022). "On the other hand, CRISPR/Cas9-edited CD96−/− human NK cells did not display significant alterations in IFN-γ and TNF-α production, degranulation, or cytotoxic activity following stimulation with the U261MG CD155+ GBM line, in contrast to other tumor cell lines used." (PMID 35203609, 2022). "However, only STINGR284S mRNA, not STINGWT mRNA, stimulated the production of anti-tumor cytokines, such as CCL5, CXCL10, IL29, IL6, IFNβ and TNFα." (PMID 36498833, 2022). "As TNFα and IL-1β inhibitors are now available to treat severe ICB induced immune related adverse events, it is encouraging that blocking these pathways did not diminish the anti-tumor responses of chemo-immunotherapy in preclinical models." (PMID 35634282, 2022). "Furthermore, in the present study, although the M2 macrophage polarization and expression of VEGR, TNF-α, BRCA1, and HER2 showed differences among the different ERα+/ERα− ratio groups, the tumor size was not significantly different." (PMID 36118080, 2022). "Similarly, nuclear protein expression of Gli1 and NF-κB p65 was significantly enhanced in tumor tissues from SW1990 cells treated with IL-1β, TNF-α and Shh, whereas no significant expression was observed in the tissues from BxPC-3 cells." (PMID 34046348, 2021). "Neutrophil activation also occurs, leading to secretion of IL-8, tumor necrosis factor (TNF)-α, monocyte chemoattractant protein (MCP)-1, and IFN-α, TRAIL expression, and degranulation, which may be beneficial or not depending on the tumor model." (PMID 33535479, 2021). "However, the TIGIT-related communication was a little stronger within hypoxia T cells, while tumor necrosis factor (TNF)- and FASLG-related communications were stronger in normoxia between T cells and tumor cells." (PMID 34956900, 2021). "Interestingly, FTO depletion restored the expression levels of TNF‐α, IFN‐γ, IL‐10, and TGF‐β, but not on IL‐17 in CAL27‐A formed tumor." (PMID 34378866, 2021). "Moreover, although it did not significantly affect the level of TNF‐α and IL‐6 in liver tissues, S3I‐201 obviously restrained the enhanced STAT3 activation and EMT change of tumour tissues in the liver injury group." (PMID 33410581, 2021).
tumor (continued). "In some rodent models, tumor and non-tumor cells in the TME (e.g., leukocytes, fibroblasts, endothelial cells) secrete inflammatory mediators such as interleukin (IL)-1, tumor necrosis factor (TNF)-α, IL-6, IL-8, IFN-α, IL-10, IL-12, TGF-β, and CXCR4." (PMID 34200240, 2021). "The involvement of the TNF-α and MMP-9/TIMP-1 complex in radiation-induced non-targeted effects led to the inhibition of tumor angiogenesis, highlighted by the 0.34-fold decrease in the MMP-9/TIMP-1 ratio in patients without AIT, which was only 0.8-fold in patients with coexisting AIT." (PMID 34298820, 2021). "In the present study, A3G was observed that participated in TNF-α signaling via NF-κB pathway from GSEA analysis, which might provide a novel strategy to improve anti-tumor immunity by blocking the non-apoptotic function of these receptors." (PMID 32742470, 2020). "In addition to isatuximab-mediated NK cell activation via engaging high-level CD38-expressing tumor cells, isatuximab treatment of purified NK cells also led to direct NK cell activation and release of IFN-γ and TNF-α in the absence of target cells." (PMID 32922390, 2020). "TNF-α was consistently overexpressed in all cells that had undergone FACS but interestingly was expressed at higher levels in 5-ALA-positive cells compared to 5-ALA negative, perhaps indicating a differing stress response between tumor and nontumor cells." (PMID 32904996, 2020). "They express CCR7 that regulate their homing to lymphonodes, lack perforin, presenting little or no ability to spontaneously kill tumor cell targets, are CD16−, and mediate immune response by secreting pro-inflammatory cytokines, such as interferon-γ and tumor necrosis factor (TNF) alfa." (PMID 32793200, 2020). "Gao and colleagues observed in different murine tumor models higher expression of CTLA-4 in intermediate ILC1s (intILC1s, being CD49a+CD49b+EOMES+), that are impaired in their ability to secrete IFN-γ but not TNF-α." (PMID 33255582, 2020). "However, in contrast to our findings with MDA-MB-231 cells (Figure 9A1), when TNFα was added to MCF-7:MSC “Contact” co-cultures, no additivity was found between TNFα and the MSCs in inducing more robust morphological changes in the tumor cells (Figure 9B1)." (PMID 31031757, 2019). "In this study, inoculation of S180 tumour significantly increased kidney pro-inflammatory cytokine TNF-α (p < 0.01) and reduced kidney anti-inflammatory cytokine IL-10 (p < 0.05) without significant effects on liver TNF-α and IL-10 in mice." (PMID 31280667, 2019). "In the present study, the absence of STAT1 significantly increased the production of Th17 cytokines (IL-17A, IL-17F, and IL-22) but not of TNF-α and IFN-γ, indicating that a lack of STAT1 signaling induces a significant change in the microenvironment that supports inflammation and tumor formation." (PMID 30235866, 2018). "Nonetheless, in the DEN-induced HCC model, CD8+ T cells produced IFNγ and TNF-α, but not IL-17; CD4+ T cells, however, were a potential source of IL-17 and could be acting as a subset with pro-tumor function (unpublished)." (PMID 30150983, 2018). "However, TNF likely originates from tumor cells in MPE9 and non-specifically triggers NF-κB activation in any tumor type irrespective of its KRAS status and MPE competence, suggesting it functions as an autocrine growth factor across tumor types." (PMID 29445180, 2018). "Irg1 induction was still observed when TNF-, IFN-γ-, IL-6-, or TLR4-KO mice were inoculated with tumors, however, we could not rule out the possibility that tumor-derived cytokines influence pResMφ." (PMID 29920191, 2018). "Epitope-I and epitope-IV were both unable to stimulate the production of IFN-γ and TNF-α in effector CD8+ T cells in vehicle- and sorafenib-treated tumor-bearing mice no matter whether they received immunization and not." (PMID 30123861, 2018).
tumor (continued). "A considerable effect of TNF-α on ATAT and ATD (but not on NAT, i.e., only on the tissues where the reprogramming of metabolism has already occurred under the influence of tumor) manifested in increase of cellular hypoxia, gelatinase activity, and SO generation rate is observed." (PMID 30581847, 2018). "In addition, exosomes purified from latent or TNFα-activated J1.1 cells enhanced HSC3 cancer cell migration at the same level (J1.1 vs. J1.1+TNF), suggesting that the pro-tumor effect of HIV-positive T-cell exosomes is independent of HIV reactivation." (PMID 30389917, 2018). "However, the expression of pro-inflammatory cytokines, such as IL-1β, IFN-γ and tumor necrosis factor-α (TNF-α), was higher in TS/A-IFN-α than TS/A-IFN-β tumors and absent parental TS/A tumor." (PMID 29050360, 2017). "Inhibition of solTNF by dominant-negative TNF biologics, blocking solTNF but not tmTNF, decreased MDSC frequency, reduced tumor growth, and prolonged survival of mice with chemically induced tumors, suggesting that solTNF was responsible for MDSC accumulation during carcinogenesis." (PMID 28890718, 2017). "Naturally occurring tumour‐specific HLA‐II‐restricted CD4+ T cells and those engineered to express HLA‐I‐restricted tumour TCRs have been reported to exhibit a mainly Th1 phenotype, where cells typically produce IFN‐γ, TNF‐α and IL‐2 but not IL‐4, IL‐5 or IL‐10." (PMID 27324616, 2017). "Compared with controls, tumor cell vaccines co-expression anti-PD-1 mAbs and GM-CSF not only release the inhibition state of PD-1+ TIL in tumor microenvironment and promote the proliferation but also facilitate IFN-γ, TNF-α and IL-2 secretion of TIL (data not shown)." (PMID 29263903, 2016). "Functionally, we demonstrate with the calcein release assay that canine CD3−/NKp46+ cells kill canine tumor cell lines without prior sensitization and secrete IFN-γ, TNF-α, IL-8, IL-10, and granulocyte-macrophage colony-stimulating factor as measured by Luminex." (PMID 27933061, 2016). "Taken together, these data suggest that both PD-1 expressing T cells and Treg cells within the tumor may have a suppressive effect on T cells secreting IFN-γ, IL-2, or TNF-α, but not Th17 cells." (PMID 27014625, 2016). "Further studies also suggested that those anti-tumor N1 cells generated in the absence of TGF-β might produce higher levels of TNF-α, MIP-1α, H2O2 and NO, that were cytotoxic to tumor cells in vitro and in vivo." (PMID 26517808, 2015). "Removing FAPα+ fibroblasts does not alter the number or subtypes of tumor infiltrating T cells, but does result in their activation and secretion of interferon-γ (IFN-γ) and tumor necrosis factor-α (TNF-α), two antitumor cytokines secreted by activated Th1 and NK cells." (PMID 26305550, 2015). "The results showed that G-CSF/IL-6 could not antagonize the priming effect of IFN-γ/TNF-α, evaluated by the activation of signaling pathways, MPO release, and tumor-suppressing effect of neutrophils." (PMID 25587026, 2014). "Moreover, in control experiments that we additionally performed for this study, the tumor cell lines U-937 and HT-29 did not display apoptotic membrane blebbing when treated with TRAIL/zVAD/CHX or TNF/zVAD/CHX." (PMID 24507727, 2014). "We could assume that endogen TNF-α plays a negative role in CRC patients, favouring the growth of CRC and tumour progression and it should therefore be considered as a tumour-promoting factor rather than cytokine with anti-tumoural activities." (PMID 26019577, 2014). "Indeed, in the presence of SKBR3 tumor cells coated with αGC/sCD1d-anti-HER2, about half of iNKT cells was positive for TNFα and IFNγ, while no intracellular cytokines were detected in the presence of the irrelevant αGC/sCD1d-anti-CEA fusion protein." (PMID 23242316, 2013).
tumor (continued). "Hyperthermic isolated limb perfusion with tumor necrosis factor-α (TNF-α) and melphalan (TM-HILP) is a promising local treatment for locally advanced STSs, such as nonresectable STSs of the limbs, and has resulted in high tumor response rates and high limb salvage rates." (PMID 23938063, 2013). "Over the course of tumour rejection, neither IFN-γ nor TNF-α was detectable (data not shown)." (PMID 24251770, 2013). "However, Salako, etal., have recently confirmed that infliximab did not reduce tumour growth in this IGROV1 model, even when co-administered with an anti-mouse TNF-α antibody." (PMID 22792380, 2012). "Indeed, even if some tumor antigen specific CD4 Treg clones were also found to secrete a diverse panel of cytokines such as IFN-γ, GM-CSF, TNF and IL5 or IL4 and IL10, in vitro, none of them was able to secrete IL2." (PMID 23284752, 2012). "Notably, most tumor cells are not per se sensitive for TNF and indeed it turned out that SMAC mimetics in addition sensitizes cells for the apoptotic action of TNF." (PMID 21738708, 2011). "Tumor necrosis factor (TNF)-related apoptosis-inducing ligand (TRAIL), a member of the TNF superfamily, could induce apoptosis in various tumor cells and virus-infected cells, but not most normal cells." (PMID 21483669, 2011). "In contrast, deletion of IKKβ gene in myeloid cells attenuated inflammatory responses and diminished expression of proinflammatory cytokines including TNF, IL-1, IL-6, and CXC chemokines, without affecting apoptosis while it resulted in a significant decrease in tumor size." (PMID 24212934, 2011). "Surprisingly, even in a model of noninflammatory tumor formation(DEN-induced hepatocarcinogenesis), NF-κB activation in macrophages (Kupffer cells) appears to stimulate tumorigenesis through the secretion of hepatomitogens such as TNFα and IL-6." (PMID 18615187, 2008). "However, the fact that tumor regression did occur in a system lacking both perforin and IFN-γ indicates that other mechanisms, such as TNF-mediated pathways, can orchestrate tumor regression." (PMID 17355640, 2007). "T, N, and M categories did not individually retain significant effects (p > 0.10) on TNF-α once tumor markers were included, indicating that the relationship between advanced disease (especially T4 and M1) and TNF-α was largely captured by the elevated tumor marker levels." (PMID 40299527, 2025). "Overall, our RIPK1 phosphorylation results reveal a pattern in which sensitized tumor cells lose pro-survival S25 phosphorylation and gain cell-death-promoting S166 phosphorylation under conditions where non-canonical IKKs fail to be recruited to the TNFR1 complex upon TNF stimulation." (PMID 41315176, 2025). "The lower levels of IL-10 cytokines, as well as the increase in TNF found in our study, suggest the M1 activation and M2 inhibition in cells transfected with HPV oncogenes, suggesting higher pro-inflammatory activity and lower anti-inflammatory activity, which does not favor tumor development." (PMID 39599846, 2024). "Additionally, we did not observe activation of innate (TNF-α and IL-6 cytokines) or adaptive immune response (neutralizing antibodies, INF-γ + CD8+ T cells) in healthy or tumor-bearing immunocompetent C57BL/6 mice injected with MB/virus complexes following ultrasound-targeted MB destruction (UTMD)." (PMID 39769460, 2024). "Interestingly, in WT mice receiving EMT6 and Fab anti-CD200R, no tumor cells were detectable after immunotherapy (tumor cell vaccination), and the CD4+ cells produced increased TNFα/IL-2/IFNγ on stimulation with EMT6 in vitro, as had been seen already in CD200RKO mice." (PMID 38540350, 2024). "6SA reduces tumor volume without diminishing the number of TILs by inducing caspase-8 mediated cell apoptosis, and also concurrently augmenting the secretion of interferon-gamma (IFN-γ) and tumor necrosis factor-alpha (TNF-α), and improves the immune microenvironment of TNBC." (PMID 37660039, 2023).